TTC29 (tetratricopeptide repeat domain 29)
Description:
Axonemal protein which is implicated in axonemal and/or peri-axonemal structure assembly and regulates flagellum assembly and beating and therefore sperm motility.
Synonyms: NYD-SP14; SPGF42; TBPP2A
Tractability: Small molecule: a structure with a bound ligand is known.
Gene: Protein-coding gene on chromosome 4 (146,706,617 to 146,945,882, reverse strand). Ensembl gene ENSG00000137473.
Subcellular location: Cytoplasm, cytoskeleton, flagellum axoneme
Subcellular location (Human Protein Atlas): Principal piece
Gene Ontology:
Biological process: cilium movement; cilium organization
Cellular component: sperm flagellum; sperm principal piece
Genetic constraint (gnomAD): Loss-of-function variants: 23 observed, 36.74 expected, observed/expected ratio (o/e) 0.63, 90% interval 0.45 to 0.89. The upper end of that interval is the gene's LOEUF score, 0.89, which puts it in group 3 of 6, group 1 being the genes least tolerant of losing a copy. Missense variants: 468 observed, 457.71 expected, observed/expected ratio (o/e) 1.02, 90% interval 0.95 to 1.1. Synonymous variants: 168 observed, 169.38 expected, observed/expected ratio (o/e) 0.99, 90% interval 0.87 to 1.13.
Homologues: Orthologues: chimpanzee TTC29 (97% identical), macaque TTC29 (94% identical), pig TTC29 (82% identical), dog TTC29 (82% identical), rabbit TTC29 (81% identical), rat Ttc29 (75% identical), mouse Ttc29 (74% identical), guinea pig TTC29 (67% identical), tropical clawed frog ttc29 (48% identical), zebrafish ttc29 (32% identical). Paralogues in human: TTC28 (19% identical), GPSM1 (16% identical), GPSM2 (15% identical), TTC24 (9% identical), RAPSN (8% identical), GPSM3 (3% identical).
Diseases named in the same sentence as TTC29 in open-access papers:
TTC29 is named in the same sentence as 2 diseases in open-access papers, as found by Europe PMC text mining. Sharing a sentence is not in itself a finding about the gene and the disease. The quoted sentences say what the papers report.
male infertility (2 papers, 2022 to 2024). The inability of the male to effect fertilization of an ovum after a specified period of unprotected intercourse. "Our study revealed the novel biallelic mutations in TTC29 in a MMAF patient, which findings expand the mutational spectrum of TTC29 and further contribute to the diagnosis, genetic counseling, and prognosis of male infertility." (PMID 36346162, 2022). "In conclusion, although the specific mechanisms underlying mutations in TTC29 that cause MMAF require further exploration, our genetic and functional analyses in an affected patient suggest that biallelic variants of TTC29 induce MMAF‐associated male infertility." (PMID 36346162, 2022). "However, in view of the limited cases of TTC29 mutations in humans, more identification of pathogenic mutations in TTC29 in patients with MMAF is important for the genetic diagnosis of male infertility." (PMID 36346162, 2022). "Therefore, we hypothesize that the significant downregulation of DEGs (CFAP70, TTC29, CCDC40, DNAAF4, SYCE3, STK36, SPI1 and EMX2) in hybrid yellow catfish is the primary cause of male infertility or reduced fertility." (PMID 38891632, 2024).
TTC29 also shares sentences with these, for which no sentence is quoted: dysplasia of fibrous (1 paper).